COX8BP (cytochrome c oxidase subunit 8B, pseudogene)
Synonyms: COX8-1; COX8H; formerly COX8B
Gene: Transcribed unitary pseudogene on chromosome 11 (253,446 to 253,558, reverse strand). Ensembl gene ENSG00000289568.
Diseases named in the same sentence as COX8BP in open-access papers:
COX8BP is named in the same sentence as 7 diseases in open-access papers, as found by Europe PMC text mining. Sharing a sentence is not in itself a finding about the gene and the disease.
COX8BP shares sentences with these, for which no sentence is quoted: Alzheimer disease (2 papers); Obesity (2); atherosclerosis (1); breast carcinoma (1); chronic kidney disease (1); diabetes (1); tumor (1).